CD9 (CD9 molecule)
Diseases named in the same sentence as CD9 in open-access papers (continued):
Sharing a sentence is not in itself a finding about the gene and the disease.
metabolic disease (6 papers, 2016 to 2026). A congenital disorder (due to inherited enzyme abnormality) or acquired (due to failure of a metabolically important organ) disorder resulting from an abnormal metabolic process. "However, recent studies on metabolic disorders have suggested that CD9 and TREM2 are markers of lipid-associated macrophages (LAMs) that produce proinflammatory cytokines in humans." (PMID 36814909, 2023). "Taken together, CD9 is involved in the macrophage response to lipids, and infiltrating CD9+ LAMs exacerbate metabolic diseases." (PMID 36814909, 2023). "It should also be noted that in this clinical group of patients with metabolic disorders, different populations of CD9-positive sEVs expressing the MMP complexes, their inhibitors, and HSPs did not correlate with CD31 and VEGF-A expression in the primary tumor." (PMID 37109070, 2023).
inflammation (5 papers, 2013 to 2025). Aberrant reaction of the microcirculation characterized by movement of fluid and leukocytes from the blood into extravascular tissues. "Our findings thus reveal a critical role for the tetraspanin CD9 in colon inflammation and suggest a novel therapeutic opportunity." (PMID 29312336, 2017). "In an IL-23/Th17-driven neutrophilic inflammation model, this subpopulation can bind to neutrophils in a CD9-dependent manner and degrade ATP via CD39 to inhibit the formation of NETosis and the activation of Th17 cells, thereby alleviating airway inflammation." (PMID 40636260, 2025). "Third, statins failed to inhibit LPS-induced lung inflammation and to prolong survival of CD9 KO mice in vivo." (PMID 24040034, 2013).
cardiac disease (2 papers, 2023 to 2024). "Access to distinct subpopulations of fibroblasts, including CD9+ reparative cells, in both the control and cardiac injury populations provides an unprecedented opportunity to investigate the role of these different cell types in normal cardiovascular development as well as in heart disease." (PMID 38081833, 2023). "Our demonstration that this subpopulation of fibroblasts expresses CD9 and can be isolated by FACS provides the first opportunity to access them and study their function in culture models of cardiac development and animal models of heart disease." (PMID 38081833, 2023).
digestive system cancer (2 papers, 2021 to 2024). A primary or metastatic malignant neoplasm involving any part of the digestive system. "Generally, the expression of CD9, CD151, Tspan1, Tspan5, Tspan8, Tspan12, Tspan15, and Tspan31 are upregulated, facilitating the migration and invasion of digestive system cancer cells." (PMID 38389703, 2024).
digestive system tumor (1 paper, 2024). "Conversely, CD9, CD151, Tspan8, Tspan1, Tspan5, Tspan31, Tspan12, and Tspan15 are upregulated and enhance digestive system tumor cell metastasis." (PMID 38389703, 2024).
renal disease (1 paper, 2019). "Finally, our study suggests a concept in which severe kidney diseases characterized by pathogenic PEC recruitment to the glomerular tuft may all depend on a CD9-dependent molecular complex that adjusts the threshold for proliferation and directional migration of these cells." (PMID 31341160, 2019).
respiratory diseases (1 paper, 2018). "In the field of respiratory diseases, CD9 appears as a negative regulator of inflammation in COPD and the use of molecules, such as statins, upregulating tetraspanin CD9 in macrophages and allowing decreases of inflammation are under consideration for therapeutic intervention." (PMID 30356731, 2018).
CD9 also shares sentences with these, for which no sentence is quoted: toxoplasmosis (7 papers); infectious disease (5); fibrosis (3); liver disease (3); metabolic dysfunction-associated steatohepatitis (3); prostate (3); astrocyte tumor (2); Chagas disease (2); Cognitive impairment (2); colon adenocarcinoma (2); dyslipidemia (2); ischemic stroke (2); lung squamous cell carcinoma (2); metastatic prostate carcinoma (2); osteoarthritis (2); Parkinson disease (2); Pleural effusion (2); prostate adenocarcinoma (2); rectal cancer (2); type 1 diabetes (2); viral disease (2); acute respiratory distress syndrome (1); adrenal carcinoma (1); airway hyperresponsiveness (1); amyloid (1); anaplastic astrocytoma (1); astrocytoma (1); B-cell acute lymphoblastic leukemia (1); basophilic leukemia (1); benign kidney tumor (1).
A further 61 diseases each share a sentence with CD9 in 1 paper.